TRBV6-4 (T cell receptor beta variable 6-4)
Description:
V region of the variable domain of T cell receptor (TR) beta chain that participates in the antigen recognition. Alpha-beta T cell receptors are antigen specific receptors which are essential to the immune response and are present on the cell surface of T lymphocytes. Recognize peptide-major histocompatibility (MH) (pMH) complexes that are displayed by antigen presenting cells (APC), a prerequisite for efficient T cell adaptive immunity against pathogens. Binding of alpha-beta TR to pMH complex initiates TR-CD3 clustering on the cell surface and intracellular activation of LCK that phosphorylates the ITAM motifs of CD3G, CD3D, CD3E and CD247 enabling the recruitment of ZAP70. In turn ZAP70 phosphorylates LAT, which recruits numerous signaling molecules to form the LAT signalosome. The LAT signalosome propagates signal branching to three major signaling pathways, the calcium, the mitogen-activated protein kinase (MAPK) kinase and the nuclear factor NF-kappa-B (NF-kB) pathways, leading to the mobilization of transcription factors that are critical for gene expression and essential for T cell growth and differentiation. The T cell repertoire is generated in the thymus, by V-(D)-J rearrangement. This repertoire is then shaped by intrathymic selection events to generate a peripheral T cell pool of self-MH restricted, non-autoaggressive T cells. Post-thymic interaction of alpha-beta TR with the pMH complexes shapes TR structural and functional avidity.
Synonyms: TRBV64; TCRBV13S5; TCRBV6S4
Gene: T-cell receptor variable (V) gene on chromosome 7 (142,380,806 to 142,381,261, forward strand). Ensembl gene ENSG00000211713.
Subcellular location: Cell membrane
Gene Ontology:
Biological process: cell surface receptor signaling pathway
Cellular component: plasma membrane
Homologues: Paralogues in human: TRBV6-1 (71% identical), TRBV6-5 (70% identical), TRBV6-6 (70% identical), TRBV6-8 (70% identical), TRBV6-2 (69% identical), TRBV6-7 (69% identical), TRBV10-1 (63% identical), TRBV10-2 (62% identical), TRBV10-3 (60% identical), TRBV27 (52% identical), TRBV25-1 (51% identical), TRBV19 (50% identical), and 39 more.
Diseases named in the same sentence as TRBV6-4 in open-access papers:
TRBV6-4 is named in the same sentence as 1 disease in open-access papers, as found by Europe PMC text mining. Sharing a sentence is not in itself a finding about the gene and the disease. The quoted sentences say what the papers report.
infection (1 paper, 2025). The state of being infected such as from the introduction of a foreign agent such as serum, vaccine, antigenic substance or organism. "Several common TRA and TRB pairs, such as TRAV1-2/TRAJ33, TRAV21/TRAJ49, TRBV6-4/TRBD2/TRBJ2-3, and TRBV5-1/TRBD1/TRBJ2-7, were consistently detected from the primary infection (PI) through the convalescent phase (HC) and into the reinfection phase (RI)." (PMID 41209021, 2025).